YBX1 (Y-box binding protein 1)
Diseases named in the same sentence as YBX1 in open-access papers (continued):
Sharing a sentence is not in itself a finding about the gene and the disease.
Obesity (6 papers, 2023 to 2026). Accumulation of substantial excess body fat. "One study showcased the pivotal role of YBX1 in driving fat accumulation, a core feature of obesity." (PMID 40732992, 2025). "Collectively, YBX1 controls autophagy and adipogenesis, positioning it as a key regulator for obesity driven by adipose tissue expansion." (PMID 40732992, 2025). "For instance, FUNDC1 deficiency impairs mitochondrial quality and exacerbates diet-induced obesity and metabolic syndrome, Parkin regulates obesity by coordinating mitophagy, and YBX1 promotes brown adipogenesis and thermogenesis through mitophagy." (PMID 41292047, 2025). "This work unveils the functional significance of YBX1 in regulating autophagy and adipogenesis, suggesting a potential therapeutic strategy for treatment of obesity and metabolic diseases." (PMID 36642732, 2023). "Our study revealed that YBX1 played a significant role in the regulation of autophagy and adipogenesis, providing a promising target to fight against obesity and related metabolic diseases." (PMID 36642732, 2023). "Collectively, these findings unveil the post-transcriptional and transcriptional mechanism and functional importance of YBX1 in autophagy and adipogenesis regulation, providing an attractive molecular target for therapies of obesity and metabolic diseases." (PMID 36642732, 2023). "Whether therapeutic benefit in the treatment of obesity might be obtained by targeting proteins such as YBX1 is an interesting question." (PMID 40498837, 2025). "Collectively, these findings suggest that YBX1 plays a distinct role in different fat depots and adipocytes, which could be a potential target for treatment of obesity." (PMID 36642732, 2023).
cardiac hypertrophy (5 papers, 2023 to 2025). "More importantly, silencing of YBX1 reversed the protective effect of lncKCND1, suggesting that YBX1 is a downstream target in the machinery of lncKCND1 regulation of cardiac hypertrophy." (PMID 39586986, 2025). "In conclusion, our results indicated that LncKCND1 interacted with YBX1 and played an important role in cardiac hypertrophy by modulating cardiac mitochondrial function." (PMID 37253771, 2023). "Knocking down Ybx1 in NRCMs resulted in smaller cells, and this effect was preserved after stimulation with PE during in vitro cardiac hypertrophy." (PMID 37378715, 2023). "The role of in vivo has not been studied to date, and this study sheds light on the protective nature of reducing Ybx1 levels in vivo in cardiac hypertrophy." (PMID 37378715, 2023). "Ribo-seq suggests a translational upregulation of Ybx1 during cardiac hypertrophy, while Ybx1 mRNA levels remain virtually unchanged according to RNA-seq." (PMID 37378715, 2023). "To clarify its regulatory role in pathological cardiac hypertrophy, we first measured the expression level of YBX1 in hypertrophic heart tissues and Ang II-induced CMs." (PMID 37253771, 2023). "In this study, we determined that LncKCND1 acts as an upstream regulator of YBX1 in cardiac hypertrophy." (PMID 37253771, 2023). "We discovered that eucaryotic elongation factor 2 (Eef2) mRNA is bound to Ybx1, and its translation is upregulated during cardiac hypertrophy dependent on Ybx1 expression." (PMID 37378715, 2023). "Mechanistically we identified around 700 transcripts that bound to Ybx1 during cardiac hypertrophy, and among this data set, we selected 7 targets that were also translational regulated by Ybx1 in cardiomyocytes." (PMID 37378715, 2023). "By combining bioinformatics analysis and molecular experiments, we established that LncKCND1 regulates cardiac hypertrophy by directly binding to Y-box binding protein 1 (YBX1)." (PMID 37253771, 2023). "Moreover, silencing YBX1 reversed the effect of LncKCND1 on cardiomyocyte mitochondrial function and its protective role in cardiac hypertrophy, suggesting that YBX1 is a downstream target of LncKCND1 in regulating cardiac hypertrophy." (PMID 37253771, 2023). "The role of YBX1 in cardiac hypertrophy has rarely been reported." (PMID 37253771, 2023). "Recognizing that LncKCND1 can bind to YBX1 and regulate its expression in pathological cardiac hypertrophy, we hypothesized that YBX1 might be a downstream regulator of LncKCND1." (PMID 37253771, 2023). "Thus, from the disease point of view, it is crucial to further research the relationship between LncKCND1 and YBX1; and their role in inhibiting pathological cardiac hypertrophy in live subjects should be investigated in future studies." (PMID 37253771, 2023). "In this study, we demonstrated that LncKCND1 could also regulate mitochondrial function by directly binding to YBX1 in cardiac hypertrophy." (PMID 37253771, 2023). "The transcription factor Y-box binding protein 1 (YB-1) can interact with transcription factors involved in cardiac hypertrophy and may thereby interfere with the hypertrophy growth process." (PMID 38203580, 2023). "Furthermore, YBX1 was downregulated during cardiac hypertrophy, whereas overexpression of YBX1 inhibited Ang II-induced cardiomyocyte hypertrophy." (PMID 37253771, 2023). "Finally, Ybx1 depletion in vivo preserved heart function during pathological cardiac hypertrophy." (PMID 37378715, 2023). "Therefore, we investigated whether YBX1 could eliminate the protective effect of LncKCND1 during cardiac hypertrophy by performing rescue experiments." (PMID 37253771, 2023).
diabetes (5 papers, 2019 to 2025). "Ybx1 was shown to be weakly expressed in the kidneys of diabetic mice, suggesting a role for this RBP in diabetes." (PMID 32104542, 2020).
head and neck cancer (5 papers, 2011 to 2024). A primary or metastatic malignant neoplasm affecting the head and neck. "In head and neck carcinoma, nuclear phosphorylation of YBX1 transcriptionally regulates the PI3K pathway and promotes the proliferation and invasion of head and neck cancer cells." (PMID 38849679, 2024). "Phospho-YBX1 is a good prognostic indicator in patients with heterogeneous head and neck cancer (HNC)." (PMID 37370092, 2023).
chronic myeloid leukemia (4 papers, 2022 to 2025). "The expression of YBX1 is significantly increased in the hematopoietic stem cells of chronic myeloid leukemia." (PMID 40799245, 2025).
colorectal tumors (4 papers, 2010 to 2023). "Our findings revealed a higher YBX1 mRNA expression in colorectal tumor tissues than in adjacent tissues." (PMID 35861369, 2023). "Then we assayed the messenger RNA expression of YBX1 and YBX1-responsive target genes by interrogating microarrays, and also expression of the YBX1 protein by immunohistochemistry in colorectal tumors." (PMID 21170361, 2010). "First, we compared the gene expression profiles of four primary colorectal tumors, in which YBX1 is up-regulated, with their matched normal tissues." (PMID 21170361, 2010).
diffuse large B-cell lymphoma (4 papers, 2018 to 2025). "Overexpression of YBX1 confers resistance to mitoxantrone by cell adhesion mechanisms in diffuse large B-cell lymphoma." (PMID 33072328, 2020). "In diffuse large B-cell lymphoma (DLBCL) cells, NSUN2 stabilized PDL1 mRNA through an m5C-dependent mechanism and YBX1-dependent pathway." (PMID 41462962, 2025).
endometrial cancer (4 papers, 2019 to 2022). Primary or metastatic malignant neoplasm involving the endometrium (mucous membrane that lines the endometrial cavity). "A previous study on ASEs in endometrial cancer also identified YBX1 as the hub SF." (PMID 33101358, 2020). "Therefore, we hypothesized that the differential expression of splicing factor YBX1 was closely related to the different types of endometrial cancer." (PMID 31355251, 2019).
fibrosis (4 papers, 2017 to 2026). the formation of excess fibrous connective tissue in an organ or tissue in a reparative or reactive process. "In vivo, intratracheal delivery of Ybx1-targeting shRNA via adeno-associated virus (AAV) robustly attenuates ECM deposition, hydroxyproline content, and fibrotic marker expression in a bleomycin (BLM)-induced murine fibrosis model." (PMID 41800249, 2026).
gynecological cancers (4 papers, 2020 to 2024). "In gynecological cancer, YBX1 was shown to be an important player impacting AKT and the downstream genes such as EGFR, Snail, or E-cadherin." (PMID 33816248, 2021).
malignant pleural mesothelioma (4 papers, 2019 to 2022). A malignant neoplasm that arises from mesothelial cells in the pleura and shows a diffuse growth pattern. "Given that downregulation of Y-box binding protein 1 (YBX1) played an inhibitive role in malignant pleural mesothelioma (MPM), miR-137 can suppress MPM progression by targeting YBX1." (PMID 34337085, 2021). "In malignant pleural mesothelioma, miR-137 and its downstream target YBX1 promote tumor invasion." (PMID 34094916, 2021).
osteoporosis (4 papers, 2024 to 2025). A condition of reduced bone mass, with decreased cortical thickness and a decrease in the number and size of the trabeculae of cancellous bone (but normal chemical composition), resulting in increased fracture incidence. "The aberrant expression of YBX1 is closely associated with tumorigenesis and age-related diseases such as osteoporosis." (PMID 39727969, 2024). "For instance, the lncRNA RAD51-AS1 in hBMSCs from patients with osteoporosis was significantly lower than those from healthy donors, it can interact functionally with Y-box binding protein 1 (YBX1), which binds to Smurf2 mRNA." (PMID 40454168, 2025). "Taken together, these results suggested that elevating the expression of Ybx1 by intravenous administration of sciadopitysin promoted CD31hiEMCNhi vessel formation and stimulated new bone formation in both aged and OVX-induced osteoporosis mouse models." (PMID 38385749, 2024).
pleural mesothelioma (4 papers, 2023 to 2025). A neoplasm that arises from the mesothelial cells of the pleura. "YBX1 plays a crucial role in pleural mesothelioma (PM) growth and migration; genetic knockdown or entinostat targeting YBX1 significantly inhibits PM cell growth and enhances sensitivity to cisplatin and radiation, particularly through increased platinum uptake." (PMID 38255791, 2024). "In recent years, research demonstrated new evidence that YBX1 may have a role in microRNA processing and contribute to the invasive characteristics of Pleural Mesothelioma." (PMID 35861369, 2023). "The non-translated region of YBX-1 linked to a luciferase reporter gene demonstrates direct binding of miR-137 to YBX-1, suppressing its expression and inhibiting Malignant Pleural Mesothelioma cell growth and colony formation." (PMID 39062595, 2024).
Premature ovarian insufficiency (4 papers, 2021 to 2026). Amenorrhea due to loss of ovarian function before the age of 40. "The down-regulated lncRNA HCP5 in the human premature ovarian insufficiency (POI) model can partially cause dysfunction of granulosa cells due to impaired DNA damage repair mediated by Y-box binding protein 1 and ILF2." (PMID 34944367, 2021). "LncRNA HCP5 helps YBX1 nuclear localization and promotes MSH5 transcription and DNA damage repair in granulosa cells from patients with premature ovarian insufficiency." (PMID 41507135, 2026).
rectal cancer (4 papers, 2013 to 2025). A primary or metastatic malignant neoplasm that affects the rectum. "The correlation was not statistically significant between YBX1 expression levels and OS in patients suffering from both colon and rectal cancer (p = 0.190, 0.930, respectively)." (PMID 35861369, 2023). "The aims of this study were to simultaneously evaluate the expression of Y-box binding protein-1 (YB-1) in non-neoplastic rectal tissue and rectal cancer tissue, and to collect clinical follow-up data for individual patients." (PMID 25790262, 2015). "Conversely, YBX1 is recognized for its transcriptional control over HR repair genes and ABC transporters in cancer, leading us to posit that YBX1, rather than IGF2BP1, is the critical substrate through which PRMT3 regulates chemoradiotherapy resistance in rectal cancer." (PMID 41147802, 2025).
acute kidney injury (3 papers, 2019 to 2024). Sudden and sustained deterioration of the kidney function characterized by decreased glomerular filtration rate, increased serum creatinine or oliguria. "CCT4, HSP90AA1, NCL, PABPC1, and YBX1 were found to be associated with kidney disease, acute kidney injury, edema, tumor metastasis, transitional cell carcinoma, necrosis, and inflammation." (PMID 37058032, 2023). "Five genes (CCT4, HSP90AA1, NCL, PABPC1, YBX1) were found to be associated with kidney disease, acute kidney injury, edema, tumor metastasis, transitional cell carcinoma, necrosis, and inflammation." (PMID 37058032, 2023). "To explore YB-1’s role in the fibrogenic response to acute kidney injury, we established an inducible Ybx1-knockout model." (PMID 38474331, 2024). "We hypothesized that Ybx1 deletion would protect against acute kidney injury and mitigate fibrosis." (PMID 38474331, 2024).
adenovirus infection (3 papers, 2015 to 2025). "Environmental stresses, such as adenovirus infection, hyperthermia, oxidative stress, UV irradiation or DNA-damaging drugs, could induce YBX-1 relocation from cytoplasm to nucleus." (PMID 26805816, 2016).
atherosclerosis (3 papers, 2021 to 2025). A disease characterized by the build-up of fatty material and calcium deposition in the arterial wall resulting in partial or complete occlusion of the arterial lumen. "Downregulation of YBX1 observed in the current study in LEAD vs. AAA subjects may indicate enhanced oxidized LDL-mediated inflammatory response and lipid deposition in macrophages, what is characteristic for pathogenesis of atherosclerosis, and hence LEAD." (PMID 33801150, 2021).
brain tumor (3 papers, 2019 to 2023). "YBX1 siRNA knockdown in GBM cell line and GBM patient derived primary brain tumor-initiating cells (BTIC) led to reduced expression of SOX258." (PMID 31358880, 2019).
chordoma (3 papers, 2019 to 2024). Chordomas are rare malignant tumors arising from embryonic remnants of the notochord in axial skeleton. "Moreover, YBX1 enhanced EGFR transcription by directly binding to its promoter in chordoma cells, thereby regulating protein expression of p-EGFR, p-AKT and its downstream target genes that influence cell apoptosis and cell cycle transition." (PMID 38255791, 2024).
colorectal adenocarcinoma (3 papers, 2011 to 2024). The most common type of colorectal carcinoma. "We found that not only is YBX1 upregulated or mutated across a broad spectrum of cancers, but its transcript levels are also significantly higher across colorectal adenocarcinoma (COAD) tumors compared to normal tissue counterparts." (PMID 32985589, 2020). "On the other hand, YBXs have a defensive function in specific categories of cancers, like YBX1 in colorectal adenocarcinoma (COAD) and THCA, along with YBX2 in stomach adenocarcinoma (STAD)." (PMID 38698857, 2024).
COVID-19 (3 papers, 2022 to 2023). A disease caused by infection with severe acute respiratory syndrome coronavirus 2. "Furthermore, four risk genes (upstream binding transcription factor, RNA polymerase II, I and III subunit L, Y-box binding protein 1 and yippee like 2) were found to be associated with COVID-19 severity." (PMID 35139909, 2022). "In the present study, four risk regulators (UBTF, POLR2L, YBX1 and YPEL2) were identified to be associated with COVID-19 severity." (PMID 35139909, 2022).
ischemic stroke (3 papers, 2023 to 2025). A stroke disorder caused by obstruction of blood flow to the brain, due to thrombotic (local blood clot formation) or embolic (due to a blood clot or other material traveling from another site) event. "Collectively, TSG facilitated PINK1/Parkin pathway-mediated mitophagy by upregulating USP10/YBX1 axis to ameliorate ischemic stroke." (PMID 39406480, 2024). "Besides, YBX1 carried by neural stem cell extracellular vesicles inhibited neuronal pyroptosis in ischemic stroke." (PMID 39406480, 2024). "Our data suggest a novel mechanism of Dex neuroprotection for ischemic stroke through regulating lncRNA HOXA11-AS by targeting the miR-337-3p/Ybx1 signaling pathway, which might help develop new strategies for the therapeutic interventions in cerebral ischemic stroke." (PMID 37059588, 2023). "Mechanically, TSG upregulated USP10 to elevate YBX1 protein expression, thereby facilitating PINK1/Parkin-mediated mitophagy and improving ischemic stroke injury." (PMID 39406480, 2024). "In this model, EVs carrying YBX1 increase m6A‐modified GPR30 stability and expression, promoting NLRP3 inflammasome ubiquitination by interacting with SPOP (speckle‐type POZ protein), ultimately suppressing neuronal pyroptosis in ischemic stroke." (PMID 40734485, 2025).
kidney cancer (3 papers, 2020 to 2026). Primary or metastatic malignant neoplasm involving the kidney. "Infiltrating CD4+ T cells fascinate TGFβ1 expression and regulated kidney cancer cell proliferation by activating TGFβ1/YBX1/HIF2α signals." (PMID 35096961, 2021).
liver disease (3 papers, 2021 to 2025). "Y-box binding protein 1 (YBX1) participates in multiple pathophysiological processes, including embryonic development, tissue repair, liver disorders, and energy metabolism." (PMID 40083711, 2025). "Moreover, gene expression analyses in patients suggest that YBX1 is clinically not only relevant for the HBV life cycle but also for the pathogenesis of virus-induced liver disease and cancer." (PMID 36591611, 2022). "Indeed, in patients, YBX1 expression is accompanied by expression of genes involved in liver disease progression, as well as lower survival of HCC patients." (PMID 36591611, 2022). "Since YBX1 is involved in the modulation of several signal transductions pathways, HBV-YBX1 interaction may also play a role in the pathogenesis of virus-induced liver disease and HCC." (PMID 36591611, 2022). "Based on our observation that HBV can modulate YBX1 expression in PHH, we next studied YBX1 gene expression in liver tissues in different cohorts of patients with HBV infection and liver disease." (PMID 36591611, 2022). "In patients, YBX1 expression robustly correlates with both HBV load and liver disease progression." (PMID 36591611, 2022).
lymphoma (3 papers, 2020 to 2023). A malignant (clonal) proliferation of B- lymphocytes or T- lymphocytes which involves the lymph nodes, bone marrow and/or extranodal sites. "Our findings indicated that HNRNPD and YBX1 are required for TCLlnc1-mediated regulation of TGF-β signaling pathway, as well as T-lymphoma cell proliferation and migration." (PMID 33767152, 2021). "TCLlnc1/HNRNPD/YBX1 complex upregulated transcription of TGFB2 and TGFBR1 genes, activated the tumor growth factor-β signaling pathway, resulting in lymphoma progression, and might be a potential target in PTCL." (PMID 33767152, 2021).
Myocardial fibrosis (3 papers, 2019 to 2023). "Our findings suggest that miR-133 and YBX-1 are potential therapeutic targets to improve myocardial fibrosis." (PMID 31443679, 2019). "We next investigated whether BPS acts on myocardial fibrosis through YBX1/GSK‐3β ultimately affecting cAMP signaling pathway." (PMID 38018586, 2023). "BPS treatment increased the binding of YBX1 to the GSK‐3β promoter, and GSK‐3β protein expression was upregulated, which further caused the upregulation of p‐CREB and cAMP, and finally inhibited myocardial fibrosis." (PMID 38018586, 2023).